SNORA10 (small nucleolar RNA, H/ACA box 10)
Synonyms: ACA10; SNORA10A
Gene: Small nucleolar RNA gene on chromosome 16 (1,962,334 to 1,962,466, reverse strand). Ensembl gene ENSG00000206811.
Gene Ontology:
Biological process: RNA processing
Cellular component: nucleolus
Homologues: Orthologues: chimpanzee SNORA10 (100% identical). Paralogues in human: SNORA10B (98% identical), SNORA64 (62% identical).
Diseases named in the same sentence as SNORA10 in open-access papers:
SNORA10 is named in the same sentence as 2 diseases in open-access papers, as found by Europe PMC text mining. Sharing a sentence is not in itself a finding about the gene and the disease.
SNORA10 shares sentences with these, for which no sentence is quoted: gastric cancer (1 paper); tumor (1).